EZR (ezrin)
Diseases named in the same sentence as EZR in open-access papers (continued):
Sharing a sentence is not in itself a finding about the gene and the disease.
T cell lymphomas (1 paper, 2015). "However, ezrin was also suggested, in another study, to inhibit TRAIL- and Fas ligand-induced cell death in T cell lymphomas." (PMID 26010871, 2015). "While the contribution of ezrin in Fas signalling has been extensively studied, little is known regarding TRAIL, with the exception of a recent study in which ezrin was proposed to impair both Fas ligand- and TRAIL-induced cell death in the tumor T-cell lymphoma cell line H9." (PMID 26010871, 2015).
tuberous sclerosis (1 paper, 2025). Hereditary disease characterized by seizures, intellectual disability, developmental delay, and skin and ocular lesions. "Here, we report that endosomal-localized EGFR/Ezrin complex interacts with and triggers the inhibition of the Tuberous Sclerosis Complex (TSC complex) in response to EGF stimuli." (PMID 39937579, 2025).
urothelial carcinoma (1 paper, 2014). A malignant neoplasm derived from the transitional epithelium of the urinary tract (urinary bladder, ureter, urethra, or renal pelvis). "The application of automated approaches may add additional value to future validatory studies, in order to further determine optimal prognostic cutoffs for ezrin expression in urothelial carcinoma." (PMID 25278252, 2014).
vivax malaria (1 paper, 2015). "However, further studies are need to explore the association of these intercellular adhesion molecules with ezrin in vivax malaria." (PMID 25889165, 2015).
tumor (267 papers, 2005 to 2026). "The increased molecular functions, on the other hand, highlight a strong association with growth factors, also related to tumor development and association with the binding of actin filaments, a function of ezrin already well described in the literature." (PMID 38972247, 2024). "Links between ezrin mRNA expression and genes identified in related pathways were explored as part of this study to determine how expression was linked in patient tumours." (PMID 36938826, 2023). "This interaction between Ezrin and S100P has been implicated in tumor cell migration, where the resulting activation of Ezrin promotes the transendothelial migration of tumor cells." (PMID 37371090, 2023). "Associations between HER2 status, tumour grade and ER status and ezrin expression, have been described previously; however, this is within the context of specific localisation patterns of ezrin." (PMID 36938826, 2023). "High ezrin expression was significantly associated with adverse survival of patients whose tumours were categorised as receptor (ER, PgR or HER2) positive (p < 0.001) in comparison to those categorised as triple‐negative breast cancer (p = 0.889)." (PMID 36938826, 2023). "Ezrin and Radixin were detected in murine brain tissue and HepG2 cells, underlining the tumor-associated Ezrin expression." (PMID 37928027, 2023). "Ezrin mRNA and protein expression were both associated with larger tumour size, higher tumour grade and HER2‐positive tumours." (PMID 36938826, 2023). "High expression of ezrin was significantly associated with larger tumour size (p = 0.027), higher tumour grade (p < 0.001), worse Nottingham Prognostic Index prognostic group (p = 0.011) and HER2‐positive status (p = 0.001)." (PMID 36938826, 2023). "Ezrin is highly expressed by circulating tumor cells, and this has been associated with higher levels of Ezrin in the bloodstream in LSCC." (PMID 37371090, 2023). "High levels of Ezrin gene expression are linked to cell proliferation, migration, invasion, and tumor differentiation." (PMID 37791063, 2023). "Much research has indicated that Ezrin overexpression is strongly associated with tumor metastasis and poor patient prognosis, acting as a key player in various cancer types." (PMID 37371090, 2023). "Ezrin is associated with defective adhesion turnover and a loss of directional migration, leading to tumor invasion and metastasis." (PMID 36355541, 2022). "DHA reversed EMT changes in tumor tissues, causing E-cadherin and p-Ezrin reinventing and the re-inhibition of Vimentin, N-cadherin, Snail, and Twist expression compared to the model group." (PMID 34539408, 2021). "Studies have linked defects in adhesion turnover to a loss of directional migration, a mechanism by which Ezrin promotes tumor cell invasion and metastasis." (PMID 33171868, 2020). "In primary cutaneous melanoma the intensity of ezrin immunoreactivity was associated with tumor thickness and the level of invasion." (PMID 33171868, 2020). "Ezrin overexpression was associated with enhanced tumor aggressiveness, while knockdown of Ezrin expression reduced the proliferation, migration, and invasion of cancer cells." (PMID 32028718, 2020). "Collectively, our results provide insight into ezrin’s role in tumorigenesis, revealing a bidirectional interaction between tumor-associated macrophages and tumor cells, and suggest myeloid cell ezrin as a target for therapeutic intervention against cancer." (PMID 33086476, 2020). "Ezrin expression is independently associated with tumor size, poor differentiation, and vascular invasion in HBV-HCC." (PMID 33240887, 2020). "In this study, Ezrin was found to be upregulated in BC tissues, which was linked with aggressive tumour characteristics and poor prognosis." (PMID 30804430, 2019).
tumor (continued). "We show that ezrin is expressed at significantly higher levels in lymph node metastases compared to matched primary tumors, and that a high tumor ezrin level is associated with increased risk of relapse in BC patients with regional disease." (PMID 30678714, 2019). "The actin microfilament-associated EZR is a key regulator of Src activity and has important function in tumor induced angio-/lymph angiogenesis." (PMID 31191821, 2019). "Compared to parental SK-KOSA cells, mtDNA depletion in SK-KOSA cells resulted in higher levels of the markers β4 Integrin, Cullin-1 and Ezrin suggesting a causal role of mtDNA depletion in the induction of the marker genes that drive tumor progression." (PMID 30576337, 2018). "Ezrin or p-ezrin overexpression has been found in diverse human cancers and has been associated with tumor progression and malignant phenotype." (PMID 27622508, 2016). "Mesothelin is a GPI anchored cell surface protein that can promote cancer cell survival and proliferation, while Ezrin plays an important role in cellular processes like cell adhesion and migration and is linked to tumor metastasis." (PMID 26840568, 2016). "The opposite effects between ezrin and 4.1 proteins on tumor progression are likely caused by opposite effects of phosphorylation on their functions." (PMID 26575790, 2016). "Ezrin or p-ezrin overexpression has been found in diverse human cancers and was associated with tumor progression and malignant phenotype." (PMID 27622508, 2016). "Taken together, the association of phosphorylated cld7 with integrins, which is accompanied by FAK activation and ezrin association, contributes to tumor cell motility and the association with MMP14 in GEM supports invasiveness." (PMID 25514462, 2015). "There is growing evidence that Ezrin expression level is associated with tumor progression and dissemination." (PMID 26632332, 2015). "In this study, cytoplasmic ezrin expression was also found to be associated with adverse tumour characteristics and survival, although the prognostic value did not remain independent of conventional clinicopathological factors." (PMID 25278252, 2014). "Tumours containing ezrin-deficient cells displayed a five-fold reduction in vascular density and a 10-fold reduction in vascular luminal area compared to MDASrc plugs (respectively)." (PMID 25231728, 2014). "Tumours derived from ezrin-deficient cells demonstrated a significant reduction in lymphangiogenesis compared to MDASrc cells, as indicated by lymphatic vessel markers lyve-1 and podoplanin (respectively)." (PMID 25231728, 2014). "Despite the small sample size, the finding of a significant reduction of membranous ezrin expression in recurrent tumours further supports the increasing body of evidence demonstrating that loss of ezrin is associated with tumour progression." (PMID 25278252, 2014). "Intravital imaging and microvessel density (MVD) analysis of tumour xenografts revealed significant reductions in tumour-induced angio/lymphangiogenesis in ezrin-deficient cells when compared to the WT or activated Src-expressing cells." (PMID 25231728, 2014). "All three animal models yielded similar reductions in vascularization of ezrin-deficient or Y477F ezrin-expressing tumour cells." (PMID 25231728, 2014). "For example, ERK/AP-1 signaling is required for transactivation of the VIL2 gene promoter, leading to Ezrin expression, the up-regulation of which has been associated with tumor invasion and metastasis of CRC cells." (PMID 23755307, 2013). "Positive ezrin and paxillin protein expression was seen in 99% and 93.7%, respectively, of urothelial tumors; downregulation of ezrin and paxillin in urothelial bladder tumors was associated with aggressive tumor features and invasiveness." (PMID 23209815, 2012). "HBV-HCC patients with ezrin over-expression were independently associated with tumor with smaller size, cirrhotic liver background, poor differentiation, and vascular invasion." (PMID 19604375, 2009).
tumor (continued). "Ezrin, as a key determinant of tumour metastasis, has been implicated as a conduit for signals between metastasis-associated cell surface molecules and signal transduction components." (PMID 17551499, 2007). "In IBC cases, elevated ezrin H score values were notably linked to high tumor grade (p = 0.002), high N stage (p = 0.045), advanced AJCC stage grouping (p = 0.043), presence of metastasis (p = 0.001), higher grade (p = 0.033), and a greater extent of DCIS and perineural invasion (p = 0.031)." (PMID 39827339, 2025). "An association between high ezrin expression and ER‐ and PgR‐negative tumours and tumours that were larger, or at a more advanced stage, has also been demonstrated, in addition to an association with lymph node metastasis; a further study has also demonstrated a similar association." (PMID 36938826, 2023). "High expression of ezrin was associated with larger tumour size (χ2 = 4.921, d.f. = 1, p = 0.027), higher tumour grade (χ2 = 16.290, d.f. = 2, p < 0.001), worse NPI prognostic group (χ2 = 8.991, d.f. =2, p = 0.011) and HER2‐positive status (χ2 = 11.675, d.f. = 1, p = 0.001)." (PMID 36938826, 2023). "High ezrin expression was significantly associated with adverse survival of patients whose tumours were categorised as receptor (oestrogen receptor (ER), progesterone receptor (PgR) or HER2) positive (p < 0.001) in comparison to those categorised as triple‐negative breast cancer (p = 0.889)." (PMID 36938826, 2023). "Notably, Ezrin is known for its oncogenic character and Ezrin overexpression has previously been associated with increased invasiveness and tumor metastasis." (PMID 37928027, 2023). "Additionally, a high level of Ezrin in tumor was reported to be associated with higher metastatic potential and shorter patient survival." (PMID 36386154, 2022). "Furthermore, low capillary count, reflecting hypoxic condition, was significantly associated with Ezrin expression (p = 0.047) and decreased tumor-specific survival (p = 0.035)." (PMID 36142656, 2022). "Furthermore, after radical prostatectomy, CTCs from Ezrin-positive PCa patients were susceptible to tumor metastasis." (PMID 35156523, 2022). "Indeed, ezrin inhibition increases drug sensitivity of tumor cells, and ezrin expression is associated with poor outcomes in OS patients." (PMID 33567616, 2021). "Our results illuminate mechanisms by which ezrin contributes to macrophage differentiation to tumor-associated macrophages within the tumor microenvironment, and re-directs its function toward pro-tumorigenic and pro-metastatic properties fundamental to cancer progression." (PMID 33086476, 2020). "In addition to being used as a diagnostic marker for BC, we found that the high expression of Ezrin was associated with phenotypes of invasion and metastasis in BC, including tumour differentiation, late TNM stage and LN metastasis." (PMID 30804430, 2019). "Ezrin overexpression is associated with poor prognosis and tumor invasiveness." (PMID 29587669, 2018). "High expression of ezrin in CRC was significantly associated with tumor progression, as indicated by LN and distant metastases, and this observation was supported by our in vitro study showing that ezrin promotes the metastatic capacity of CRC cells by enabling cell invasion and migration." (PMID 29291001, 2017). "An analysis performed on tumor samples from fifty patients with STS showed a significant association between positive ezrin immunoreactivity and inferior progression-free and overall survival, as well as an association with the development of distant metastasis during follow-up." (PMID 28246524, 2017). "In univariate analysis, high ezrin expression was significantly associated with tumor progression and poor prognosis, which was consistent with our in vitro findings that ezrin promotes the metastatic capacity of CRC cells by enabling cell invasion and migration." (PMID 29291001, 2017).
tumor (continued). "In line with several recent studies, loss of ezrin expression, in particular its membranous subcellular location, was found to be associated with tumours of more advanced T-stage and higher grade, and an independent predictor of a reduced 5-year overall survival." (PMID 25278252, 2014). "In another recent study comprising 104 tumours of different stages and grades, loss of membranous ezrin expression was found to correlate with higher grade and stage, and invasiveness, but the associations with disease progression and survival were not reported." (PMID 24885195, 2014). "Furthermore, intravital microscopy revealed a robust and functional vascular network invading the MDASrc tumours, whereas vessels in the ezrin-deficient tumours were only found at the tumour periphery." (PMID 25231728, 2014). "In both cohorts, reduced membranous ezrin expression was significantly associated with more advanced T-stage (p < 0.001), high grade tumours (p < 0.001), female sex (p = 0.040 and p = 0.013), and membranous expression of podocalyxin-like protein (p < 0.001 and p = 0.009)." (PMID 24885195, 2014). "Analyses of the relationship between membranous staining and established clinicopathological factors revealed strong, significant associations between reduced membranous ezrin expression and more advanced T-stage and high grade tumours in both cohorts (p < 0.001 for all)." (PMID 24885195, 2014). "We used primary tongue SCCs to determine the frequency of ezrin overexpression and the correlations of ezrin expression with the Ki-67 index and the apoptotic index, which reflect contributions of cell proliferation and cell loss, respectively, to tumor growth and aggressiveness." (PMID 23357878, 2013). "Alterations of ezrin expression can mediate many changes in the metastasis-associated cell surface signals and intra-cellular signaling cascade that confer the metastatic capability in tumor cells." (PMID 23894313, 2013). "In addition, a high expression of fascin-1 (P = 0.007) or ezrin (P = 0.047) was associated with advanced tumor stage (T3+T4)." (PMID 23209815, 2012). "Ezrin is associated with malignant progression and metastasis in a variety of human neoplasias." (PMID 23209815, 2012). "The Ezrin protein encoded by the EZR gene was a membrane-cytoskeleton junction protein that could interact with a variety of growth factor receptors and adhesion molecules to mediate a variety of basic cell functions and promote tumor metastasis." (PMID 38438882, 2024). "In addition, accumulated evidence suggests that ezrin plays an essential role in both the maintenance of migratory and invasive capacity of tumor cells through the specific interaction with some tumor-associated plasma membrane proteins, which leads to the metastatic behavior of tumor cells." (PMID 33974673, 2021). "Finally, as a low tumor ezrin level is associated with improved DFS in node-positive and high-risk node-negative BC, a less aggressive treatment regimen may be warranted in these patients to improve quality of life." (PMID 30678714, 2019). "The overall high level and/or atypical localization of ezrin in tumor cells were shown to correlate with poor prognosis in breast cancer." (PMID 40075218, 2025). "The FERM domain, a member of the ezrin, radixin, and moesin family, is particularly noteworthy for its ligand-binding capabilities and potential to inhibit tumor growth." (PMID 39976799, 2025). "Radixin is considered the dominant form of ERM protein in primary human hepatocytes, while ezrin was mainly found in immortal human tumor cell lines." (PMID 40723305, 2025). "Emerging evidence has highlighted the pivotal role of the EWSR1/Ezrin signaling axis in tumor progression and metastasis." (PMID 40762284, 2025). "High ezrin expression was associated with poor prognostic factors such as advanced AJCC stage, higher tumor grade, advanced N stage, and presence of metastasis and perineural invasion." (PMID 39827339, 2025).